TCTN2 (tectonic family member 2)
Description:
Component of the tectonic-like complex, a complex localized at the transition zone of primary cilia and acting as a barrier that prevents diffusion of transmembrane proteins between the cilia and plasma membranes. Required for hedgehog signaling transduction (By similarity).
Synonyms: C12orf38; TECT2; FLJ12975; MKS8; JBTS24
Tractability: Antibody: UniProt predicts a signal peptide or a membrane-spanning region. PROTAC: ubiquitination databases record sites on it; its protein half-life has been measured.
Gene: Protein-coding gene on chromosome 12 (123,671,110 to 123,708,399, forward strand). Ensembl gene ENSG00000168778.
Subcellular location: Membrane; Cytoplasm, cytoskeleton, cilium basal body
Subcellular location (Human Protein Atlas): Golgi apparatus; Microtubules; Primary cilium transition zone
Pathways (Reactome):
Organelle biogenesis and maintenance: Anchoring of the basal body to the plasma membrane
Gene Ontology:
Biological process: cilium assembly; protein localization to ciliary transition zone; smoothened signaling pathway
Cellular component: ciliary membrane; ciliary transition zone; MKS complex; membrane
Genetic constraint (gnomAD): Loss-of-function variants: 64 observed, 79.46 expected, observed/expected ratio (o/e) 0.81, 90% interval 0.66 to 0.99. The upper end of that interval is the gene's LOEUF score, 0.99, which puts it in group 4 of 6, group 1 being the genes least tolerant of losing a copy. Missense variants: 761 observed, 866.17 expected, observed/expected ratio (o/e) 0.88, 90% interval 0.83 to 0.93. Synonymous variants: 292 observed, 336.07 expected, observed/expected ratio (o/e) 0.87, 90% interval 0.79 to 0.96.
Gene-disease validity (ClinGen):
ClinGen rates the evidence that TCTN2 causes each of these diseases.
Joubert syndrome 24 (autosomal recessive): Definitive.
Homologues: Orthologues: chimpanzee TCTN2 (99% identical), macaque TCTN2 (94% identical), pig TCTN2 (73% identical), rabbit TCTN2 (73% identical), rat Tctn2 (69% identical), mouse Tctn2 (68% identical), guinea pig TCTN2 (65% identical), tropical clawed frog tctn2 (40% identical), zebrafish tctn2 (35% identical), Caenorhabditis elegans tctn-1 (11% identical). Paralogues in human: TCTN3 (19% identical), TCTN1 (17% identical).
Diseases named in the same sentence as TCTN2 in open-access papers:
TCTN2 is named in the same sentence as 23 diseases in open-access papers, as found by Europe PMC text mining. Sharing a sentence is not in itself a finding about the gene and the disease. The quoted sentences say what the papers report.
ciliopathy (6 papers, 2012 to 2021). A genetic disorder of the cellular cilia or the cilia anchoring structures, the basal bodies, or of ciliary function. "We investigated multiple mouse models of human ciliopathies (including Tctn2, Cc2d2a, and Tmem231 mutants) and discovered that each displays hypotelorism, a narrowing of the midface." (PMID 34672258, 2021). "The highest intensity points of TMEM67 and TCTN2 occurred at the same axial level as MKS1 and RPGRIP1L, indicating a special axial level accommodating these ciliopathy-associated proteins." (PMID 26365165, 2015). "We also observed that knockdown of ciliopathy genes ALMS1, BUBR1 [BUB1B], IFT80, NPHP1, NPHP8 [RPGRIP1L], TCTN2, TMEM216 and TUB retarded neuronal migration." (PMID 26206566, 2015).
Joubert syndrome (6 papers, 2013 to 2025). Joubert syndrome (JS) is characterized by congenital malformation of the brainstem and agenesis or hypoplasia of the cerebellar vermis leading to an abnormal respiratory pattern, nystagmus, hypotonia, ataxia, and delay in achieving motor milestones. "Other mutations in TCTN2 were found to cause Joubert syndrome." (PMID 31428121, 2019). "We also summarized the TCTN2 mutations reported so far in patients with Meckel–Gruber syndrome (MKS) and Joubert syndrome (JS)." (PMID 41317100, 2025). "To this end, we focused on the Tectonic 2 (TCTN2) gene which is crucial for ciliary transition zone architecture and which, like INPP5E, is mutated in Joubert Syndrome." (PMID 32840212, 2020). "We examined the genes IFT57 (mutated in orofaciodigital syndrome (OFD, OMIM #311200)), BBS2 (Bardet-Biedl syndrome (BBS, OMIM #209900)), (TMEM231 (Meckel-Gruber syndrome (MKS, OMIM #249000)), TCTN2 (Joubert syndrome, (JBTS, OMIM #213300))." (PMID 32445086, 2020). "It is particularly striking that roughly 40% of the Joubert syndrome-associated genes, i.e., CC2D2A, CEP290, NPHP3, RPGRIP1L, TCTN2, TMEM216, and TMEM67, are also mutated in the closely related, but more severe, Meckel–Gruber syndrome." (PMID 22829176, 2013). "When the transmembrane domain of TCTN2 is deleted or its key sites are altered, this can disrupt the protein network to varying degrees and then induce the occurrence of Meckel syndrome (MKS) or Joubert syndrome (JS) type 24 depending on the responses of different downstream elements." (PMID 41317100, 2025).
Meckel-Gruber syndrome (4 papers, 2016 to 2025). "The wide expression pattern of TCTN2 in human tissues suggests that mutations in the TCTN2 gene are likely to be the cause of the extensive and heterogeneous phenotypes of Meckel syndrome type 8." (PMID 41317100, 2025). "The syndrome most frequently found was Meckel syndrome, diagnosed in five fetuses although caused by four different genes (CEP290 in two cases and CC2D2A, TCTN2, and MSK1 in one case each)." (PMID 34682862, 2021). "However, we also observed a trend where genes that cluster in the same ciliary compartment tended to cause a similar phenotype; e.g., mutations in the transition zone genes CC2D2A, TCTN2, TMEM237, and CEP290 almost always resulted in either Joubert or Meckel-Gruber syndrome phenotypes." (PMID 27894351, 2016).
colon cancer (1 paper, 2017). "All these data indicate that TCTN2 is associated with human cancers among which the highest expression level was found in colon cancer." (PMID 29221125, 2017). "TCTN2 association with colon cancer was also confirmed by using Receiving Operator Characteristic curves analysis." (PMID 29221125, 2017). "An interesting aspect to be elucidated is whether the cilium defect caused by loss of TCTN2 expression also contributes to the altered migratory/invasive phenotype of colon cancer cells." (PMID 29221125, 2017). "Notwithstanding our IHC data clearly showed a main TCTN2 association with colon cancer, we did not found any remarkable peak of TCTN2 expression in colon cell lines vs the other tested cancer cell lines." (PMID 29221125, 2017). "It would be interesting to investigate whether TCTN2 expression in colon cancer could increase in response to specific signal or environmental conditions." (PMID 29221125, 2017).
colorectal cancer (1 paper, 2017). A primary or metastatic malignant neoplasm that affects the colon or rectum. "This mAb mainly detected TCTN2 in colorectum cancer (63.8%; P value <0.0001), as compared to lung (18%), and ovary (16%) cancer samples, with marginal or negative staining in tested normal samples." (PMID 29221125, 2017). "In this study, we report for the first time the presence of TCTN2 in a significant percentage of colorectal cancer (CRC) as well as lung and ovary cancers." (PMID 29221125, 2017).
Intellectual disability (1 paper, 2023). "Compared to other JS-associated genes, TCTN2 gene mutations are more likely to result in intellectual disability and less likely to result in renal, hepatic, or retinal involvement." (PMID 37735380, 2023).
Nystagmus (1 paper, 2022). Rhythmic, involuntary oscillations of one or both eyes related to abnormality in fixation, conjugate gaze, or vestibular mechanisms. "The genetic variants of TCTN3, CC2D2A, TMEM231, and TCTN2 were related to the clinical subgroups with nystagmus or retinopathy." (PMID 35456484, 2022).
ovary (1 paper, 2017). "To better characterize TCTN2 protein expression and localization in tumors we selected a panel of breast, lung, colon, and ovary tumor cell lines." (PMID 29221125, 2017).
ovary cancers (1 paper, 2017). "Here we identify that TCTN2 is overexpressed in colorectal, lung and ovary cancers." (PMID 29221125, 2017).
cancer (2 papers, 2017 to 2021). A tumor composed of atypical neoplastic, often pleomorphic cells that invade other tissues. "Taken together, our results indicate that TCTN2 acts as an oncogene, making it an interesting cancer-associated protein and a potential candidate for therapeutic applications." (PMID 29221125, 2017). "Indeed, loss of TCTN2 reduced the ability of four cancer cell lines to form colonies independently of a solid surface and, remarkably, it increased cell apoptosis; it also influences cell viability, though to a moderate extent." (PMID 29221125, 2017). "Interestingly, we found that TCTN2 is expressed in the plasma membrane of cancer cell lines probably associated to the cilium." (PMID 29221125, 2017). "The initial category, containing ANKHD1, ATXN8OS, HSPB8, LSM7, MAFB, and TCTN2, is involved in the direct regulation of cancer cell proliferation, apoptosis, and cancerization." (PMID 34235216, 2021). "TCTN2 over-expression in cancer cells resulted in an increased ability to form colonies in an anchorage independent way." (PMID 29221125, 2017). "In this study we demonstrated that TCTN2 plays an important role in the growth of cancer cells by using targeted epigenetic editing." (PMID 29221125, 2017). "The fraction of samples with moderate/strong TCTN2 staining moderately decreases in stage 4 and grade 3 cancers than in less advanced and low grade cancers." (PMID 29221125, 2017). "On the other hand, downregulation of TCTN2 using targeted epigenetic editing in cancer cells significantly reduced colony formation, cell invasiveness, increased apoptosis and impaired assembly of primary cilia." (PMID 29221125, 2017). "We found that TCTN2 is expressed in cell lines derived from different cancers, and it is associated to the plasma membrane, but not protruding towards the extracellular side." (PMID 29221125, 2017). "Conversely, TCTN2 over-expression increases the clonogenic property of cancer cells." (PMID 29221125, 2017). "We then assessed whether enforced TCTN2 downregulation influences viability and growth of cancer cells." (PMID 29221125, 2017). "Moreover, it would be interesting to test whether, as reported for TCTN1 in GMB, TCTN2 could represent a prognostic factor for TCTN2-over-expressing cancers." (PMID 29221125, 2017). "As described for TCTN1, variation of TCTN2 expression could affect the interaction of the TCTN complex with MSK1 and influences its expression in the cilia, thereby leading to Wnt and Shh signaling transduction that can ultimately result in aberrant growth of cancer cells." (PMID 29221125, 2017). "Afterwards, we assessed TCTN2 localization by confocal microscopy in HCT15, HOP92 and HT29 cancer cell lines, by permeabilizing or not the cell membrane with the detergent BRJ96." (PMID 29221125, 2017).
tumor (1 paper, 2017). "Additionally, we found that loss of TCTN2 caused by transient silencing significantly affects cell invasiveness, suggesting a role for the protein in the development of the tumor cell ability to penetrate the surrounding tissues leading to the formation of metastasis." (PMID 29221125, 2017). "The influence of TCTN2 downregulation on tumor aggressiveness was assessed in HT-29 cells using in vitro assays measuring features like cell invasiveness and clonal growth in anchorage independent conditions." (PMID 29221125, 2017). "TCTN2, taking part to a supramolecular functional complex with TCTN1, could act in combination with it in conferring cellular phenotypes relevant for tumor growth and spread to distal sites." (PMID 29221125, 2017). "The TCTN2 protein was detected in 93% of the cases (21.5% with a strong or moderate staining), with no remarkable differences in detection frequency among tumor staging and grading histological criteria." (PMID 29221125, 2017).
TCTN2 also shares sentences with these, for which no sentence is quoted: Bardet-Biedl syndrome (1 paper); gastric cancer (1); lymphoma (1); microphthalmia (1); nephronophthisis (1); non-small cell lung carcinoma (1); occipital encephalocele (1); orofaciodigital syndrome (1); polycystic kidneys (1); retinal diseases (1); retinopathy (1); sarcoma (1).